ELMO1 (engulfment and cell motility 1)
Description:
Regulates the activity of DOCK guanine nucleotide exchange factors (GEFs). Acts in association with DOCK1, DOCK2, DOCK5 and CRK. Promotes RAC1 activation by DOCK5; the activity is stimulated by RHOG. Involved in cytoskeletal rearrangements required for phagocytosis of apoptotic cells and cell motility.
Synonyms: KIAA0281; CED12; ELMO-1; CED-12
Tractability: Small molecule: a structure with a bound ligand is known. Antibody: its Gene Ontology location is reachable by antibodies, with high confidence; UniProt places it where antibodies can reach, with medium confidence. PROTAC: ubiquitination databases record sites on it; its protein half-life has been measured.
Gene: Protein-coding gene on chromosome 7 (36,852,906 to 37,449,223, reverse strand). Ensembl gene ENSG00000155849.
Subcellular location: Cytoplasm; Cell membrane
Pathways (Reactome):
Disease: FCGR3A-mediated phagocytosis; Nef and signal transduction
Signal Transduction: PTK6 Regulates RHO GTPases, RAS GTPase and MAP kinases; VEGFA-VEGFR2 Pathway
Cell-Cell communication: SRC activates STAT3 in a quantitative manner, through Cadherin-11 (CDH11), RAC1 and gp130 (IL6ST)
Immune System: Regulation of actin dynamics for phagocytic cup formation
Gene Ontology:
Molecular function: guanyl nucleotide exchange factor activator activity; protein binding; SH3 domain binding; guanyl-nucleotide exchange factor activity
Biological process: actin cytoskeleton organization; cell motility; phagocytosis, engulfment; Rac protein signal transduction; actin filament organization; apoptotic process; regulation of vasculogenesis
Cellular component: cytoplasm; guanyl-nucleotide exchange factor complex; membrane; plasma membrane; cytosol; glutamatergic synapse; postsynapse
Genetic constraint (gnomAD): Loss-of-function variants: 24 observed, 98.42 expected, observed/expected ratio (o/e) 0.24, 90% interval 0.18 to 0.34. The upper end of that interval is the gene's LOEUF score, 0.34, which puts it in group 1 of 6, group 1 being the genes least tolerant of losing a copy. Missense variants: 614 observed, 961.69 expected, observed/expected ratio (o/e) 0.64, 90% interval 0.6 to 0.68. Synonymous variants: 343 observed, 360.85 expected, observed/expected ratio (o/e) 0.95, 90% interval 0.87 to 1.04.
Homologues: Orthologues: mouse Elmo1 (99% identical), rat Elmo1 (99% identical), macaque ELMO1 (99% identical), pig ELMO1 (99% identical), dog ELMO1 (99% identical), guinea pig ELMO1 (99% identical), rabbit ELMO1 (99% identical), chimpanzee ELMO1 (95% identical), tropical clawed frog elmo1 (93% identical), zebrafish elmo1 (86% identical), zebrafish si:dkey-56f14.7 (22% identical). Paralogues in human: ELMO2 (75% identical), ELMO3 (52% identical), ELMOD1 (9% identical), ELMOD3 (9% identical), ELMOD2 (8% identical).
Diseases named in the same sentence as ELMO1 in open-access papers:
ELMO1 is named in the same sentence as 85 diseases in open-access papers, as found by Europe PMC text mining. Sharing a sentence is not in itself a finding about the gene and the disease. The quoted sentences say what the papers report.
diabetic nephropathy (18 papers, 2010 to 2026). "Mutations in the human ELMO1 gene are linked with diabetic nephropathy and, in animal models of this disease, high ELMO1 levels promote renal dysfunction." (PMID 42156725, 2026). "A recent meta-analysis on the genetic map of diabetic nephropathy reported ELMO1 rs741301 to significantly increase the risk of diabetic nephropathy (DN) in diabetics with normoalbuminuria." (PMID 38277369, 2024). "This study aim was to systematically review and explore the association between ELMO1 gene polymorphisms and diabetic kidney disease." (PMID 38277369, 2024). "ELMO1 is required for phagocytosis of apoptotic cells and cell motility, and single nucleotide polymorphisms (SNPs) tagged to ELMO1 are associated with diabetic nephropathy in T1D and T2D39,40." (PMID 33753784, 2021). "The results of our meta-analysis suggested that ELMO1, which is associated with the development and progress of diabetes nephropathy in humans, is a candidate gene for CONF." (PMID 28118822, 2017). "The last underlined gene, engulfment and cell motility 1 (ELMO1), is a susceptible gene in diabetic nephropathy, and hypertension is highly prevalent in diabetic nephropathy patients." (PMID 27980639, 2016). "A meta-analysis of genetic associations in diabetic nephropathy showed that rs741301 of ELMO1 was associated with diabetic nephropathy in Asians with type 2 diabetic nephropathy (OR 1.58 [95 % CI 1.28–1.94])." (PMID 27761430, 2015). "Notably, SNPs in the Engulfment and Cell Motility 1 (ELMO1) gene have been associated with kidney diseases such as diabetic nephropathy and nephrotic syndrome." (PMID 41300434, 2025). "An association with the ELMO1 gene and diabetic nephropathy was initially identified in patients with type 2 diabetes mellitus and this association has now also been reported for diabetic nephropathy in T1D." (PMID 20687937, 2010). "ELMO gene variants have been associated with diabetic kidney disease, especially for ELMO1, which promotes the development of nephropathy in diabetic mice, and was suggested to promote the development of glomerular injury through dysregulation of the extracellular matrix (ECM)." (PMID 35874819, 2022). "Our prior studies have demonstrated that genetically increased Elmo1 expression in mice aggravated several kidney pathologies including diabetic nephropathy and transition of AKI to chronic kidney disease induced by IRI." (PMID 41841030, 2026). "This is in accordance with our research conducted on zebrafish embryos, but is in contrast to a recent published study which suggested that low ELMO1 expression prevents diabetic nephropathy development in mice." (PMID 27849017, 2016). "Future prospects should thus focus on the induction of ELMO1 in diabetic conditions, in order to compensate for unfavorable effects of hyperglycaemia on the renal structure, contributing to diabetic nephropathy." (PMID 27849017, 2016). "In this study, we have established an important role of ELMO1 in renal function, under hyperglycaemic conditions, within the zebrafish and successfully translated our finding to the pathogenesis of human diabetic nephropathy." (PMID 27849017, 2016). "Previous research has suggested that the ELMO1 gene may play a role in the development of diabetic kidney disease." (PMID 38277369, 2024). "Thus, this study aimed to identify the role played by ELMO1 in renal development in zebrafish, under hyperglycaemic conditions, and in diabetic nephropathy patients." (PMID 27849017, 2016). "Thus, we expect that an upregulation of ELMO1 in the diabetic patients would likely protect the nephron from increased apoptosis, ultimately delaying the onset of diabetic nephropathy." (PMID 27849017, 2016). "ELMO1 may play a role in diabetic kidney disease in Iranian individuals as a population with high prevalence of T2DM, DN and ESRD." (PMID 27761430, 2015).
diabetic nephropathy (continued). "However, the functional role of ELMO1 in human and zebrafish kidneys, with respect to diabetic nephropathy, is currently unknown and is in the need to be established." (PMID 27849017, 2016). "In the ethnic subgroup analysis, significant differences for diabetic nephropathy in terms of diabetes duration (≥10 years) were observed for CCL2 rs3917887, CCR5 rs1799987, ELMO1 rs74130, and IL8 rs4073." (PMID 37187702, 2023). "Specific variations in RAGE, ELMO1 and TGF-β1 genes, and their gene-environment interactions, have been found to be associated with diabetic nephropathy in the Han Chinese population, but have not been investigated in the Chinese diaspora, where environmental exposures may be different." (PMID 35226673, 2022).
breast carcinoma (11 papers, 2014 to 2023). "Previous reports have shown that the association between ELMO1 and Gαi2 contributes to actin polymerization in human breast cancer cells." (PMID 32292657, 2020). "ELMO1 is associated with metastasis in several cancers, and is part of the chomokine regulated pathway, including Rac1 and Rac2, that regulates the actin cytoskeleton in metastatic breast cancer." (PMID 30557297, 2018). "ELMO1 (engulfment and cell motility 1) together with Dock180 as a complex plays an important role in promoting cancer cell invasion which has been shown for gliomas, breast cancer, and ovarian cancer." (PMID 31340858, 2019). "As an activation of Src leads to an elevation of the complex consisting of p130Cas/Crk/Dock180 in breast cancer cells, ELMO1/Dock180 binding must be important for producing Src-dependent activation of Rac1." (PMID 26205662, 2015). "Previous studies have shown that increased expression of ELMO1 was responsible for the malignant behavior of ovarian and breast cancer, as well as glioma cells." (PMID 25360637, 2014). "Interestingly, ELMO family members such as ELMO1 and ELMO3 have been implicated in a variety of malignant cancers, such as glioma, breast cancer, colorectal cancer, hepatocellular carcinoma, and non-small-cell lung carcinoma." (PMID 32292657, 2020). "In breast cancer cells, Axl can phosphorylate ELMO1/2 to promote Rac activation and cell invasion." (PMID 30345300, 2018). "The ELMO1, DOCK1, and RAC1 pathway has been implicated in: phagocytosis of Gram-negative bacteria by macrophages, T cell migration in primary lymphocytes, and actin cytoskeleton regulation during breast cancer metastasis." (PMID 25901943, 2015). "In human breast cancer, it is the first time that ELMO1/DOCK180 and Rac molecular synergistically activate the processes of breast cancer cells chemotaxis and metastasis." (PMID 37251542, 2023). "In breast cancer cells, Gαi2 regulates the activation of Rac proteins through the GEF activity of Elmo1/Dock180 (Engulfment and cell motility 1/dedicator of cytokinesis) interaction, contributing on the actin polymerization and migration." (PMID 36092739, 2022).
glioma (9 papers, 2012 to 2025). A benign or malignant brain and spinal cord tumor that arises from glial cells (astrocytes, oligodendrocytes, ependymal cells). "A similar effect was found when ELMO1, another motility-related adaptor molecule strongly implicated in the aggressiveness of gliomas, was knocked down." (PMID 26377974, 2015). "ELMO1 encodes a cell motility protein that contributes to glioma cell invasion." (PMID 32528944, 2020). "In glioma, DOCK1 and engulfment and cell motility 1 (ELMO1) were reported to promote human glioma cell invasion." (PMID 38415469, 2025). "A molecular complex, functioning as a GEF for Rac, including engulfment and cell motility 1 (ELMO1) and dedicator of cytokinesis 1 (Dock180) (ELMO1/Dock180) has been identified as a key player in migration and invasion of glioma cells." (PMID 35011682, 2021). "In addition, the migratory and invasive abilities of glioma cells increase with the level of ELMO1 expression." (PMID 32292657, 2020). "For instance, ELMO1 was clearly related to the invasive phenotype of glioma cells." (PMID 32292657, 2020). "In contrast to a prior report on ELMO1, a regulator of GTPase activation and glioma cell motility, our study suggest that the crosstalk between the CD151-integrin complexes and RTKs converge at ARHGAP26, consistent with its link to the EGFR-mediated cell motility and signaling." (PMID 26377974, 2015). "Importantly, ELMO1, by forming the complex with dedicator of cytokinesis 180 (Dock180), serves as a Rac1 guanine nucleotide exchange factor that stimulates glioma cell migration and invasion." (PMID 22494416, 2012).
Nephropathy (9 papers, 2015 to 2025). A nonspecific term referring to disease or damage of the kidneys. "Several genes, including UMOD, SHROOM3 and ELMO1 have been strongly associated with renal diseases, and some of their traits, such as eGFR and creatinine." (PMID 30359254, 2018). "Several genes, including UMOD, SHROOM3 and ELMO1 have been strongly associated with renal diseases, and some of their traits, such as eGFR and serum creatinine." (PMID 30359254, 2018). "Later studies have demonstrated that variants in the ELMO1 gene are associated with kidney disease attributed to T2DM in American Indians, European Americans and Chinese population." (PMID 27761430, 2015). "Remarkably, worldwide genetic studies in humans reported a susceptibility of diabetic patients with gene variants of ELMO1, ELMO2 or ELMO3 to develop kidney damage." (PMID 35874819, 2022). "Studies analyzing the role of ELMO1 in kidney function described an aggravation of nephropathy in mice with type 1 diabetes and a promotion of glomerular injury through dysregulation of the extracellular matrix (ECM) in presence of ELMO1." (PMID 35874819, 2022). "ELMO1 promoter methylation roles are also reported in human colorectal cancer, kidney disease, and rheumatoid arthritis." (PMID 28418867, 2017). "In spite of this, the precise role of ELMO1 in the development and progression of nephropathy attributed to T2DM is still unknown." (PMID 27761430, 2015). "Thus, our study suggests that the work performed on zebrafish embryos, can be translated to a clinical setting, where ELMO1 could protect the diseased kidney from increased apoptosis, irrespective of the underlying renal disease." (PMID 27849017, 2016). "In this study, we examined the role of high Elmo1 expression in kidney damage progression at one month and four months after unilateral IRI, using wild-type (WT) and Elmo1H/H mice, which express approximately twice the WT level of Elmo1 mRNA." (PMID 41300434, 2025). "Thus, histological results indicate that ELMO1 is equally expressed in different kidney diseases and not differentially regulated, due to a specific pathological condition." (PMID 27849017, 2016). "This study aimed to assess the expression levels of ACE, ELMO1, and WT1 mRNAs in the blood extracellular vesicles (EVs) of DN patients and diabetic patients without nephropathy (DM group) in comparison to healthy controls and investigate their correlations with the severity of DN." (PMID 34246281, 2021).
Arthritis (7 papers, 2021 to 2025). Inflammation of a joint. "Here, we show that ELMO1 acts as a signaling hub affecting the function of osteoclasts, cells that mediate bone degradation, to promote bone loss in arthritis and osteoporosis." (PMID 34404802, 2021). "In mice arthritis model induced by K/BxN serum or collagen, Elmo1 deficiency can relieve the inflammatory response and cause a better outcome of the disease by reducing the accumulation of neutrophils." (PMID 34993193, 2021). "Collectively, we identify ELMO1 as a signaling hub that regulates osteoclast function and bone loss, with relevance to osteoporosis and arthritis." (PMID 34404802, 2021). "However, the ankle thickness in Elmo1–/– mice was significantly lower than it in Elmo1+/+ mice after 12 days of serum transfer, suggesting that Elmo1 deficiency ameliorates the progression of arthritis." (PMID 34381782, 2021). "Therefore, we tested whether ELMO1 plays a role in bone loss during arthritis via two mouse models—collagen-induced arthritis and K/BxN serum-induced arthritis." (PMID 34404802, 2021). "Additionally, loss of the apoptotic cell-engulfment signaling protein ELMO1 alleviated disease severity in mouse models of arthritis through regulation of neutrophil chemotaxis to inflamed joints, and ELMO1 knockdown reduces human neutrophil migration to chemokines linked to inflammatory arthritis." (PMID 34101054, 2021). "Recent studies have revealed that adenovirus therapy targeting ELMO1 delays the inflammatory response in an arthritis animal model, and that the c-terminal helical inhibitory peptide of ELMO1 decreases osteoclast-mediated bone resorption." (PMID 37175809, 2023). "Consistent with its role in cell migration, ELMO1-dependent movement of neutrophils to inflamed joints contributes to arthritis progression." (PMID 34404802, 2021). "After injection of Av-ELMO1, the arthritis score were significantly reduced, and the disease incidence time was delayed in the injected group compared to the control groups." (PMID 34508078, 2021). "As expected, both Elmo1+/+ and Elmo1–/– mice injected with K/BxN serum developed severe arthritis compared to the PBS-injected controls, manifesting the onset of clinical signs and increase of ankle thickness within 6 days." (PMID 34381782, 2021). "Thus, in both the acute and chronic models of arthritis, ELMO1 contributes to the bone erosions, likely due to function in macrophage lineage cells such as osteoclasts." (PMID 34404802, 2021). "We further explored these serum indices of osteoclast number and activity in Elmo1+/+DBA and Elmo1−/−DBA mice under healthy and collagen-induced arthritis conditions." (PMID 34404802, 2021).
rheumatoid arthritis (5 papers, 2017 to 2025). A chronic, systemic autoimmune disorder characterized by inflammation in the synovial membranes and articular surfaces. "(D) ELMO1 locus plot showing association to rheumatoid arthritis (RA), primary biliary cholangitis (PBC), multiple sclerosis (MS), chromatin accessibility, and ELMO1 expression in lymphoblastoid cell lines (LCLs)." (PMID 41396161, 2025). "Contrary to DOCK2 (Dedicator of Cytokinesis 2) deficiency, which has been reported to be associated with immunodeficiency diseases, variants of ELMO1 have been associated with autoimmune diseases, such as diabetes and rheumatoid arthritis (RA)." (PMID 34993193, 2021). "Recently, we found that Elmo1 deficiency suppresses the adhesion and migration of osteoclast precursors, which are critical processes for the information of mature osteoclasts, and results in alleviated bone erosion in Elmo1 knockout mice in a rheumatoid arthritis mouse model." (PMID 37175809, 2023). "Importantly, we show that bone erosion is alleviated in Elmo1–/– mice in a rheumatoid arthritis mouse model." (PMID 34381782, 2021). "Furthermore, we discovered that bone erosion is alleviated in Elmo1 knockout mice in rheumatoid arthritis model." (PMID 34381782, 2021). "Interestingly, we also demonstrated in this study that bone erosion in Elmo1–/– mice is alleviated in a K/BxN serum transfer induced rheumatoid arthritis model, indicating that ELMO1 also affects bone resorption by osteoclasts." (PMID 34381782, 2021). "Conversely, analyses of genetic polymorphisms in different human populations around the world found that ELMO1 was associated with autoimmune diseases such as diabetes, rheumatoid arthritis, and nephropathy, but not immunodeficiency diseases." (PMID 34993193, 2021).
autoimmune disease (4 papers, 2017 to 2025). A disorder resulting from loss of function or tissue destruction of an organ or multiple organs, arising from humoral or cellular immune responses of the individual to their own tissue constituents. "As a member of the ELMO1-DOCK2 protein complex, it is known that DOCK2 deficiency can lead to inherent immunodeficiency diseases in the human population, whereas genetic polymorphism studies have shown that ELMO1 variants are associated with autoimmune diseases." (PMID 34993193, 2021). "Thus, studies on Elmo1 in mouse models indicated that altered Elmo1 functions changed the function of immune cells and regulated the progression of autoimmune diseases." (PMID 34993193, 2021). "Moreover, ELMO1, which previously had not been associated with autoimmune diseases, showed eQTL colocalization with RA, PBC, and MS association signals." (PMID 41396161, 2025). "Many of these genes have either known roles in Treg differentiation, stability and function (CD48, IL6ST, EZR, ELMO1, IL18R1), or altered expression in human Treg in autoimmune disease (SLAMF1, ANKRD55, TAGAP)." (PMID 35773720, 2022).
diabetes (4 papers, 2016 to 2023). "Therefore, this study is aimed at investigating the association of a genetic polymorphism of CCL2-rs3917887, CCR5-rs1799987, ELMO1-rs74130, and IL8-rs4073 with the development of DN among Malaysian type 2 diabetes mellitus (T2DM) patients." (PMID 30713847, 2019).